ANLN (anillin, actin binding protein)
Diseases named in the same sentence as ANLN in open-access papers (continued):
Sharing a sentence is not in itself a finding about the gene and the disease.
cancer (continued). "Our present data demonstrated that ANLN was directly regulated by antitumor miR-217 and knockdown of ANLN significantly inhibited cancer cell aggressiveness in PDAC cells." (PMID 28881803, 2017). "Silencing ANLN expression markedly inhibited cancer cell migration and invasion capabilities of PDAC cell lines." (PMID 28881803, 2017). "Our data showed that several pathways were downstream from ANLN, such as the “focal adhesion”, “pathways in cancer”, “ECM-receptor interaction” and “regulation of the actin cytoskeleton”." (PMID 28881803, 2017). "Overexpressed ANLN was reported in several cancers and elevated expression appears to be involved in the metastatic potential of human cancers." (PMID 28881803, 2017). "Consistent with the prominent role of ANLN during cytokinesis, up-regulation of ANLN expression is frequently observed during cancer development, growth and progression." (PMID 27863473, 2016). "Our findings indicate that miR-497 is a potent tumor suppressor that inhibits cancer phenotypes by targeting ANLN and HSPA4L in NPC." (PMID 26486082, 2015). "Several studies have demonstrated an overexpression of ANLN in cancer such as in several of the UM tumors assayed in the present study." (PMID 21647268, 2011). "Moreover, significant positive correlations between VIRMA or IGF2BP3 protein expression and ANLN protein expression were observed in human pan-cancers." (PMID 41513610, 2026). "Functional studies indicated that ANLN was involved in cancer cell proliferation and cell cycle." (PMID 41513610, 2026). "Integrating multi-omics approaches, cross-cancer comparative analyses, and RNA interference or gene-editing technologies may accelerate the clinical translation of ANLN-targeted therapies." (PMID 41573677, 2025). "Genetic studies further supported the protective effect of ANLN knockdown in cancer formation." (PMID 40704506, 2025). "ANLN is overexpressed in various cancer types and is closely associated with tumor proliferation, migration, invasion, and EMT, and it is linked to poor prognosis in cancer patients." (PMID 41573677, 2025). "Innovatively, we developed a prognostic risk model using LASSO and Cox regression on three hub genes (WDR72, ANLN, SLC16A12), integrating multi-omics data for immune microenvironment, tumor mutation burden (TMB), cancer stem cell (CSC) index, and drug sensitivity assessment." (PMID 41332473, 2025). "The causal relationship between ANLN dysregulation and tumor initiation is not fully established, the cancer-specific regulatory networks governing its activity are incompletely understood, and effective, highly specific ANLN inhibitors are still lacking." (PMID 41573677, 2025). "High ANLN levels strongly correlate with increased tumor migration, invasion, metastasis, and poor clinical outcomes, making it a potential prognostic biomarker with broad predictive value across multiple cancer types." (PMID 41573677, 2025). "Similarly, ANLN exhibits increased expression across various cancers and thus is considered an oncoimmunological biomarker." (PMID 40236649, 2025). "As a key regulator of cell division, ANLN promotes tumor cell proliferation and drives malignant progression by orchestrating cell-cycle progression and ensuring cytokinetic fidelity across multiple cancer types." (PMID 41573677, 2025). "ANLN is an actin-binding protein that is required in cytokinesis, localized at the cleavage furrow with roles in preserving its structural integrity, that was suggested as a potential target for cancer treatment." (PMID 39268460, 2024). "Consequently, blocking the PI3K/AKT signaling pathway can potentially counteract the cancer-promoting effects of ANLN in GBC cells." (PMID 38398143, 2024). "The prognostic risk model based on six DMGs in our study, namely FAM83A, S100A16, E2F7, ANLN, C1QTNF6 and GAPDH, suggests that they might reveal causes of the cancer development and tumorigenesis in LUAD." (PMID 38711158, 2024).
cancer (continued). "Furthermore, ANLN knockout of BC cells induced dramatic transcriptional reprogramming, and resulted in the suppression of cancer cell stemness and trans-differentiation from mesenchymal to epithelial lineages." (PMID 39728605, 2024). "Finally, our assays demonstrated that the overexpression of ANLN had cancer-promoting functions in BC cells." (PMID 39728605, 2024). "However, we also found that ANLN expression was negatively connected to CD8+ T cells in some cancer types." (PMID 36030492, 2023). "Furthermore, we explored the correlation between ANLN expression and different clinical features across pan‐cancer." (PMID 36030492, 2023). "Anillin (ANLN) is a mitosis-related protein that promotes contractile ring formation and cytokinesis, but its cell cycle-dependent degradation mechanisms in cancer cells remain unclear." (PMID 36526897, 2023). "We assessed the association between ANLN expression and TMB/MSI across 31 cancers." (PMID 36030492, 2023). "To conclude, ANLN proved to be a promising marker for future cancer management." (PMID 36199577, 2022). "On the whole, ANLN was correlated with the expression of immunoinhibitors in pan-cancer." (PMID 36199577, 2022). "It is tempting to speculate that ANLN contributes to the malignant phenotype by enhancing mitotic rounding and allowing cancer cells to divide." (PMID 35710398, 2022). "Besides affecting the cell cycle, recent studies have found previously underappreciated functions of nuclear ANLN, including controlling transcriptional programming and regulating the stemness and differentiation of cancer cells." (PMID 36199577, 2022). "The ROC curve was then introduced and we revealed the predictive value of ANLN in pan-cancer." (PMID 36199577, 2022). "To understand whether ANLN expression affected the prognosis of tumor patients, we utilized the PrognoScan database to get an ANLN expression-based survival analysis of cancer patients." (PMID 36199577, 2022). "ANLN is abnormally overexpressed in almost all cancer tissues compared with normal tissues." (PMID 35340220, 2022). "In addition, ANLN expression was strongly associated with that of DEPDC, KIF14, KIF23, RACGAP1, and CKAP2L genes across cancers." (PMID 35340220, 2022). "Overall, these data suggested that ANLN may be a prognostic biomarker associated with patient OS, DFI, and PFI in human cancers." (PMID 35340220, 2022). "Final Cox regression analyses unveiled that ANLN could serve as an independent prognostic biomarker for certain cancers." (PMID 36199577, 2022). "Finally, we classified the tumor samples into subgroups according to different ANLN expression levels to observe its influence on cancers." (PMID 35340220, 2022). "ANLN expression is generally overexpressed in various types of cancers, and it may have an important influence on tumor progression and development." (PMID 35340220, 2022). "Together, these findings suggest that ANLN may be a predictive marker for patient prognosis across cancers." (PMID 35340220, 2022). "Therefore, we investigated the relationship of ANLN methylation levels with prognosis in patients with cancer." (PMID 35991576, 2022). "Furthermore, ANLN expression was strongly correlated with the levels of immunosuppressive cells in almost all cancer types." (PMID 35991576, 2022). "However, the upstream factors regulating the expression of ANLN and why ANLN is consistently upregulated in various cancer types are undefined and await further investigations." (PMID 35340220, 2022). "Overexpression of ANLN may disrupt the normal regulatory mechanism by influencing the actin-myosin cytoskeleton in events other than cytokinesis, thus directly promoting cancer progression." (PMID 35340220, 2022).
cancer (continued). "Taken together, ANLN is proved to be a novel and promising biomarker for its excellent predictive utility, promising prognostic value, and potential immunological roles in pan-cancer." (PMID 36199577, 2022). "In the final, ANLN exhibits high accuracy in predicting many cancers, and subsequent multivariate analysis suggests ANLN could be an independent prognostic factor in specific cancer types." (PMID 36199577, 2022). "As far as we know, our research was the first to come up with the assumption that ANLN might affect cellular senescence in the malignant tumor, although the mechanism is still unclear and remains to be elucidated minutely." (PMID 36199577, 2022). "ANLN was considered to play an oncogenic role in cancer development." (PMID 35800432, 2022). "In our study, we provide an overview of ANLN’s roles in pan-cancer, which includes gene expression, prognostic value, molecular mechanisms, immunological roles, predictive value, and tumor heterogeneity, indicating that ANLN is a potential therapeutic biomarker for malignancies." (PMID 36199577, 2022). "Meanwhile, ANLN was differentially expressed in different molecular subtypes of ten cancer types." (PMID 36199577, 2022). "Moreover, heatmap analysis also showed that these genes were positively correlated with ANLN expression in various cancers, including GBM and LGG." (PMID 35568883, 2022). "ANLN showed a significant positive correlation with tumor immune cell infiltration only in COAD, KIRC, LIHC, and PRAD, indicating that ANLN could enhance tumor immune infiltration through T-cell dysfunction in these cancer types." (PMID 35991576, 2022). "Numerous studies have implied that ANLN is overexpressed in a variety of human cancers." (PMID 35340220, 2022). "In addition, in 17 types of cancer, ANLN expression is increased in early tumor stages, and higher ANLN expression predicts worse survival outcomes in more than ten cancers." (PMID 36199577, 2022). "The cancer cases were classified into two subgroups based on the ANLN expression levels." (PMID 35340220, 2022). "In conclusion, our results showed that ANLN expression was increased in various types of tumors and that ANLN expression was correlated with prognosis, suggesting that ANLN may be a prognostic indicator for certain cancers, particularly LIHC." (PMID 35568883, 2022). "Surprisingly, depriving of ANLN in cancer cell cytokinesis inhibited the development of liver tumors in mice without interfering with the regeneration of normal liver cells, which may provide superior referential value for future tumor treatment." (PMID 36199577, 2022). "To sum, both ANLN mRNA and protein were upregulated in most cancers." (PMID 36199577, 2022). "We evaluated the effect of ANLN expression on chemotherapy response in a clinical cancer cohort." (PMID 35991576, 2022). "Herein, we first presented a systematic and comprehensive analysis of ANLN in human carcinoma." (PMID 35340220, 2022). "ANLN was alsoabundantly expressedin the cancer cell lines CAL27 and HN30." (PMID 34082790, 2021). "ANLN is highly expressed in a variety of cancers and promotes the development of cancer." (PMID 34675301, 2021). "Selected by LASSO model, ANLN, TTK, AIM1L and person neoplasm cancer status might be candidate parameters associated with OS in HCC patients." (PMID 34130591, 2021). "ANLN, a protein coding gene, is highly expressed in many cancers." (PMID 34530829, 2021). "ANLN is a conserved actin-binding protein that exerts its functions in cytoskeletal dynamics during cell division and may affect cancer progression through Wnt/B-catenin pathway in GC." (PMID 34354996, 2021). "Among these, we observed the ANLN was highly correlated with multiple cancer pathways, molecular function, and cell components, revealing ANLN may play a pivotal role in MIBC development." (PMID 33604353, 2020).
cancer (continued). "ANLN has been identified as a biomarker in a variety of human cancers." (PMID 32903581, 2020). "Moreover, the roles of ANLN in cancer development in both cytokinesis and outside should be further characterized." (PMID 32560530, 2020). "Studies of the ANLN-specific inhibitor as well as of the role of ANLN in cancer development, especially its role outside the cytokinesis event, are of paramount importance and could bring many benefits to cancer treatment." (PMID 32560530, 2020). "It is imperative to discover compounds that could specifically inhibit ANLN, because these putative ANLN inhibitors could help deeply understand the role of ANLN in events outside cytokinesis, and its interactions with oncoproteins in cancer development." (PMID 32560530, 2020). "Evidence indicates that ANLN still has roles outside cytokinesis, and these roles are maybe related to cancer development." (PMID 32560530, 2020). "Although there have been findings pointing to a contribution of ANLN to the development of cancer, the association of ANLN to cancer remains not fully understood." (PMID 32560530, 2020). "Taken together, this suggests that ANLN could have a direct or indirect impact on actin activities both outside and inside cytokinesis events, which could be related to cancer progression." (PMID 32560530, 2020). "Moreover, Oncomine analysis of cancer vs. normal tissue showed that ANLN and KIF18A were highly expressed in multiple HCC datasets." (PMID 31392101, 2019). "That is, by transiting triple negative cancer cells to a less malignant state via concomitantly modulating ANLN and KDR gene expression, we could obtain desired clinical results using the same strategy as that for luminal cancers." (PMID 31636652, 2019). "Previous studies have shown that ANLN is upregulated in many cancers and may serve as a promising prognostic biomarker for cancer." (PMID 31395079, 2019). "ANLN expression was reported to be correlated with cancer development and progression." (PMID 30103211, 2018). "Interestingly, some of these genes are known to be over-expressed in cancer or associated with poor prognosis such as PLK1, ANLN and FBXO530–32." (PMID 29777112, 2018). "Therefore, considering its great impact on cell cycle regulation and cancer development, it would be necessary to discover the upstream regulator of ANLN expression." (PMID 30103211, 2018). "As we proved that ANLN-targeting siRNA was effective at inhibiting cancer cell growth and invasion, ANLN might become a candidate target for development of anticancer drugs." (PMID 28600503, 2017). "Moreover, our data showed that reduced expression of ANLN in PDAC cells suppressed cancer cell migration and invasion." (PMID 28881803, 2017). "Up-regulation of ANLN in tumor specimens is a marker of poor prognosis in several cancers." (PMID 26486082, 2015). "ANLN has been demonstrated as a marker of poor prognosis, relating to aggressive cancer phenotypes." (PMID 23547718, 2013). "The identification of cell cycle associated with many DEGs, including PLK1, ANLN and KIF18B/20A, across human cancers demonstrates that the most essential characteristic of cancer cells is sustained proliferation, and that this may lead to adverse survival outcomes." (PMID 38096046, 2024). "However, the role of ANLN in pan‐cancer remains still unclear." (PMID 36030492, 2023). "This suggested that ANLN might serve as an important clinical marker for early cancer detection." (PMID 36199577, 2022). "Additionally, ANLN is correlated with immune or chemotherapeutic outcomes in malignant cancers." (PMID 35991576, 2022). "Our findings suggested that ANLN participated in tumorigenesis and cancer progression and may have applications as a promising biomarker of immune infiltration and prognosis in various cancers." (PMID 35568883, 2022). "In addition, ANLN expression increased in early tumor stages in most cancers." (PMID 36199577, 2022).
cancer (continued). "At present, little evidence of ANLN expression associated with immunity is provided in cancers." (PMID 35340220, 2022). "Therefore, it is necessary to analyze the role of ANLN from a pan-cancer perspective." (PMID 36199577, 2022). "These findingssuggest that ANLN might be a critical factor in the metastasis oforal cancer." (PMID 34082790, 2021). "Hence, we highlight the hallmarks of cancer that are impacted by ANLN and discuss them as follows." (PMID 32560530, 2020). "The conclusion is that ANLN could be a potent target for cancer treatment, but the roles ANLN, other than in cytokinesis and its influence on tumour microenvironment remodeling in cancer development, must be further elucidated, and specific ANLN inhibitors should be found." (PMID 32560530, 2020). "Interestingly, we found that ANLN showed a stronger correlation with multiple cancer pathways, biological functions, and cell components, suggesting that ANLN may be a pivotal gene in MIBC development, consistent with previous findings." (PMID 33604353, 2020). "Therefore, probably by sharing an analogous mechanism, ANLN dysregulation may lead to human cancer from various origins, including HCC." (PMID 30103211, 2018). "Patients with elevated ANLN expression level was correlated with poorer cancer-specific (median, 22.4 vs. 37.3 months, p = 0.001), progression-free (median, 19.7 vs. 27.9 months, p = 0.001) and recurrence-free survival (median, 17.1 vs. 25.2 months, p = 0.011) compared with low ANLN expression." (PMID 28600503, 2017). "Proteins, including TOP2A, BPI, PSAT1, ANLN, and TFRC, were upregulated in five of the six cancer types." (PMID 41049442, 2025). "Among these therapeutic targets, we focused on ANLN (miR-195-5p target) and MAD2L1 (miR-195-3p target) and revealed their cancer-promoting functions in LUAD cells." (PMID 40723231, 2025). "ANLN enhances EMT, stabilizes the mesenchymal phenotype, maintains cancer stemness, and promotes cell migration." (PMID 41573677, 2025). "Among the downstream signaling pathways regulated by ANLN, the PI3K/AKT pathway is the most consistently activated across cancer types." (PMID 41573677, 2025). "To investigate the signaling pathways influenced by ANLN and MAD2L1 in cancer, we generated genome-wide gene expression profiles using A549 cells transfected with siANLN or siMAD2L1." (PMID 40723231, 2025). "In conclusion, our study illustrated elevated ANLN expression in GBC tissues and its role in promoting cancer through the activation of the PI3K/AKT signaling pathway." (PMID 38398143, 2024). "ANLN was positively related with TMB, MSI, immune cells infiltration and immune checkpoint genes in various cancers." (PMID 36030492, 2023). "However, the role of ANLN in pan‐cancer prognosis and tumor immunity remains unclear." (PMID 36030492, 2023). "Based on the standardized pan-cancer dataset in the UCSC database, we analyzed ANLN gene expression in the samples." (PMID 36526897, 2023). "PCR and immunohistochemical experiments on BLCA and paracancerous normal mucosal tissues showed that the expression of the ANLN gene is upregulated in BLCA, especially in MIBC and high-grade cancers." (PMID 37051591, 2023). "We evaluated the potential carcinogenic roles of ANLN using TIMER2 and Gene Expression Omnibus databases with 33 types of cancers." (PMID 35568883, 2022). "Moreover, ANLN is significantly in tumor progression in several types of human malignant tumors; however, it remains unclear whether ANLN acts through common molecular pathways within different tumor microenvironments, pathogeneses, prognoses and immunotherapy contexts." (PMID 35991576, 2022). "Furthermore, we also found that ANLN expression was linked to the infiltration levels of many immune cells, and it could predict the immune checkpoint blockade (ICB) response in specific cancers." (PMID 36199577, 2022).